METTL1 (methyltransferase 1, tRNA methylguanosine)
Diseases named in the same sentence as METTL1 in open-access papers (continued):
Sharing a sentence is not in itself a finding about the gene and the disease.
cancer (continued). "In our current research, we have discovered that METTL1 plays a crucial role in regulating the production of 5’tRFs, which trigger a stress response in cancer cells, ultimately leading to enhanced sensitivity to genotoxic agents." (PMID 37660182, 2023). "In various cancer types, METTL1 inactivation through phosphorylation at Ser27 by protein kinase B (PKB) α and ribosomal S6 kinase (RSK) was responsible for driving tumor invasion and metastasis." (PMID 37612540, 2023). "Taken together, our findings suggest that METTL1 plays a role in regulating cancer cell stress responses." (PMID 37660182, 2023). "Consistent with our functional in vitro and in vivo data on PCa, recent studies have highlighted the oncogenic role of METTL1 in several cancer types." (PMID 37516825, 2023). "Overexpression of METTL1, on the other hand, leads to oncogenic cell transformation and cancer growth, including colon cancer, lung cancer, and intrahepatic cholangiocarcinoma." (PMID 36681801, 2023). "Collectively, our findings reveal a therapeutically actionable role of METTL1-directed m7G tRNA methylation in cancer cell translation control and tumour biology." (PMID 37516825, 2023). "Another methyltransferase, METTL1, has also been shown to influence cancer progression based on its regulation of microRNA processing." (PMID 37596681, 2023). "In this regard, our study identifies that increased expression of the tRNA methyltransferase METTL1 and elevated 7-methylguanosine deposition in tRNAs have oncogenic potential by altering the translational programme in cancer cells." (PMID 37516825, 2023). "Further investigations into the relationship between METTL1 expression and response to chemotherapy will be valuable in refining personalised cancer therapeutics." (PMID 37660182, 2023). "Our study unveils the significance of m7G methylation of tRNAs in stress responses and highlights the potential of targeting METTL1 to enhance the sensitivity of cancer cells to therapy." (PMID 37660182, 2023). "To further investigate METTL1 expression in self-renewing cells of human cancer, we employed an in vitro model utilising formation by cancer stem cells." (PMID 37660182, 2023). "Nevertheless, the precise mechanism by which METTL1 connects the regulation of catabolic pathways and the fitness of cancer cells remains poorly understood." (PMID 37660182, 2023). "Depletion of METTL1 sensitises cancer cells to stress, resulting in heightened cytotoxic responses to conventional cancer treatments both in vitro and in vivo." (PMID 37660182, 2023). "METTL1 is also upregulated in other tumour types, which highlights the potential of METTL1 inhibitors as novel therapeutic options in cancer." (PMID 37660182, 2023). "We then carried out functional enrichment analysis of genes whose mRNA and m7G levels were down-regulated by knockdown of METTL1 and found that these genes were mainly enriched in transcriptional dysregulation in cancer, etc. pathways." (PMID 37599359, 2023). "In contrast, re-expression of only a catalytically active version of METTL1 promotes the proliferation of cancer cells, suggesting that METTL1-mediated RNA methylation has oncogenic potential." (PMID 37516825, 2023). "Perhaps conventional cancer treatment paired with specific METTL1 inhibitors can achieve better therapeutic effect." (PMID 37710294, 2023). "Despite being one of the most indispensable m7G-related genes, the overall relevance of METTL1 in cancer remains mostly unclear." (PMID 36118897, 2022). "To assess the expression of METTL1 more comprehensively, we conduct METTL1 gene activity based on a gene set containing on hundred genes which were most related to METTL1 expression in pan-cancer." (PMID 35432338, 2022). "We appraised the correlation between METTL1 expression and the response to drugs in multiple cancer cell lines." (PMID 35432338, 2022).
cancer (continued). "Previous studies have reported that m7G-related regulators, in particular, METTL1 and WDR4, were associated with the prognosis of cancer patients." (PMID 36226166, 2022). "Collectively, this study provides evidence for elucidating immunotherapeutic effect of METTL1 in a variety of cancers, which is likely to be instrumental for further research." (PMID 35432338, 2022). "And in many kinds of cancer, imbalance of internal RNA m7G modification induced by dysregulation of METTL1 or WDR4 played an important role in tumorigenesis." (PMID 36396627, 2022). "In our current study, the METTL1 expression pattern of pan-cancer was revealed and the fundamental effects of METTL1 on the immunosuppressive TME were examined." (PMID 35432338, 2022). "METTL1 levels were found to not only be higher in cancer patients, but also have an inverse relationship with survival for cancers such as bladder cancer." (PMID 35721477, 2022). "As the most studied methyltransferase involved in m7G-related processes, METTL1 usually forms a complex with WDR4, and its overexpression is often associated with some malignant tumors such as intrahepatic cholangiocarcinoma." (PMID 36532001, 2022). "As the core confirmed transmethylase of m7G modification, METTL1 has been reported in certain human cancers." (PMID 36396627, 2022). "Considering the robust correlation between METTL1 and KIRC, LGG, and LIHC, we enquired the potential pathways concerning METTL1 signaling in pan-cancer using GSEA." (PMID 35432338, 2022). "METTL1 and WDR4 are upregulated in various types of cancers, which are associated with poor prognosis in patients with cancers such as esophageal squamous cell carcinoma, intrahepatic cholangiocarcinoma, and nasopharyngeal carcinoma." (PMID 36313441, 2022). "METTL1 is mapped to chromosome 12 (12 q13-14), a region known to be frequently amplified in cancers." (PMID 35986847, 2022). "To explore the role of m7G tRNA modification in cancer, we first analyzed The Cancer Genome Atlas (TCGA) datasets and revealed that both METTL1 and WDR4 mRNAs are elevated in multiple cancers." (PMID 35304469, 2022). "This study provides insight into the correlation of METTL1 with tumor immune infiltration and stemness in pan-cancer, revealing the significance of METTL1 for cancer progression and guiding more effective and generalized therapy strategies." (PMID 35432338, 2022). "Increased METTL1 expression was related to adverse prognosis in 14 cancers, especially LGG and LIHC, as well as with high immune infiltration of regulatory T cell, resting mast cell, and M2 macrophage." (PMID 35432338, 2022). "Meanwhile, a tumor-promoting interaction (interleukin 1 beta (IL1β)–interleukin A receptor type 2 (IL1R2)) between cancer cells and macrophages is also suppressed in METTL1-knockout mice." (PMID 35590385, 2022). "Pan-cancer analysis showed that WDR4 and METTL1 were closely related to cancer immune infiltration and were immunotherapy targets in patients, and the high expression of KIRC was associated with poor prognosis of patients." (PMID 36147333, 2022). "Previous research has established that the expression levels of the METTL1 and WDR4 components of the tRNA m7G methyltransferase complex are dramatically increased in human cancer samples and are negatively linked with patient prognosis." (PMID 35614925, 2022). "Using the cBioportal database, we examined the pan-cancer changes in METTL1 and WDR4 in the TCGA database." (PMID 36226166, 2022). "The overexpression of METTL1 increases chemosensitivity of CC cells to cisplatin, because within the carcinoma treating process, the chemoresistance regulating process was crucially affected by METTL1-mediated m7G." (PMID 36118897, 2022). "Of the 30 METTLs, expressions of eight (METTL1, METTL7B, METTL5, NTMT1, METTL2A, METTL2B, EEF1AKNMT, METTL6) were significantly (FDR < 0.05) associated with unfavorable overall survival across cancers." (PMID 34285249, 2021).
cancer (continued). "Recently, it was reported that METTL1‐mediated m7G tRNA modification plays a major part in cancer progression." (PMID 34898034, 2021). "A recent study reported that METTL1 can promote miRNA let-7e processing in an m7G modification-dependent manner, which is involved in the regulation of cancer progression." (PMID 34778277, 2021). "Survival analysis was performed by comparing the relationship between METTL1 expression and survival time and status of the patients with cancer." (PMID 34838021, 2021). "The expression of METTL1 was found to be lower in normal human blood and brain tissues than in other normal tissues, whereas it was similar across various cancer cell lines." (PMID 34838021, 2021). "Our results indicated that DEGs under METTL1 knockout and overexpression were enriched in cancer‐related pathways, such as the PI3K‐Akt, MAPK and BC signalling." (PMID 34936728, 2021). "To explore the potential function of the m7G tRNA modification in BC, we first assessed m7G tRNA methyltransferase METTL1 mRNA expression in BC data from the TCGA (the cancer genome atlas) database." (PMID 34936728, 2021). "GO analysis indicated that METTL1 knockout and rescue DEGs were involved in cancer‐related biological processes, including cell adhesion, cell cycle and angiogenesis." (PMID 34936728, 2021). "Loss-of-function analysis in large cohorts of tumor cell lines indicated the biological importance of METTL1, an m7G methyltransferase, in cancer cell growth and survival." (PMID 34285249, 2021). "Loss-of-function analysis in tumor cell lines indicated the biological importance of METTL1, an m7G methyltransferase, in cancer cell growth and survival." (PMID 34285249, 2021). "The TCGA Pan-Cancer cohort showed six genes [METTL1, METTL11B, EEF1AKNMT, METTL18, EEF1AKMT3 (METTL21B), RRNAD1 (METTL25B)] with high-level amplifications above 2%." (PMID 34285249, 2021). "In this study, the differential expression and prognostic importance of METTL1 were evaluated in various cancer types using multiple bioinformatics databases." (PMID 34838021, 2021). "Our current proteomic and loss-of-function analysis also indicated the essential roles of WDR4 in METTL1’s biological function in human cancer." (PMID 34285249, 2021). "Data from five publicly available databases were used to analyze METTL1 expression across different tumor types and its differential expression between carcinoma and adjacent normal tissues." (PMID 34838021, 2021). "Methyltransferase-like 1 (METTL1) mediated 7-methylguanosine (m7G) is crucial for the regulation of chemoresistance in cancer treatment." (PMID 31866582, 2019). "Methyltransferase-like 1 (METTL1) was the best characterized enzyme mediating m7G methylation, which was crucial for the regulation of cancer development and chemosensitivity." (PMID 31866582, 2019). "A simultaneous overexpression of NSUN2 and METTL1 is widely observed among human cancers suggesting that targeting of both proteins provides a novel powerful strategy for cancer chemotherapy." (PMID 25233213, 2014). "Here, we provide evidence that tRNA methyltransferases, NSUN2 and METTL1, strongly influences 5-FU sensitivity in human cancer cells." (PMID 25233213, 2014). "Interestingly, another study revealed that METTL1 promotes cancer metastasis by catalyzing the upregulation of specific tRNA types by m7G, thereby promoting the translation of certain cancer-related genes." (PMID 40360483, 2025). "While METTL1 predominantly acts as an oncogenic driver in most malignancies, emerging evidence reveals its context-dependent tumor-suppressive functions in specific cancer types." (PMID 40809384, 2025). "METTL1 influences stromal cell differentiation and function: METTL1 significantly impacts stromal cell differentiation and specific functional states, such as immunosuppressive activity and cytokine secretion profiles, across multiple cancer types." (PMID 40809384, 2025).
cancer (continued). "METTL1, an RNA m7G methyltransferase, plays a pivotal role in multiple cancers." (PMID 41562049, 2025). "Collectively, these data suggest that METTL1 may function as an oncogene in cancer by regulating glycolysis and mitochondrial metabolism." (PMID 39979979, 2025). "Furthermore, m5C modification-related proteins, including FMRP and members of the NSUN family, as well as the key m7G tRNA modification enzyme METTL1, have been reported to be involved in regulating the radiotherapy response in malignant tumors." (PMID 40823093, 2025). "Third, tumor heterogeneity may lead to variable dependence on METTL1 inhibition across different cancer types, requiring systematic validation in large-scale clinical cohorts." (PMID 41562049, 2025). "Furthermore, METTL1 expression demonstrates unique correlations with tumor immune infiltration and cancer stemness indices." (PMID 41562049, 2025). "In addition, METTL1 expression was significantly correlated with stemness indices in multiple tumors, excluding a few cancer types, further suggesting a potential role in regulating tumor stemness and immune-related features." (PMID 41562049, 2025). "Additionally, epigenetic modifications such as lactylation and m6A methylation further contribute to the dynamic regulation of METTL1 in cancer cells, highlighting its complex control and potential as a therapeutic target (seeFigure 1)." (PMID 41562049, 2025). "The data reviewed here reveal that METTL1 exerts context-dependent roles in cancer biology, either promoting or suppressing tumorigenesis through m7G-mediated regulation of RNA metabolism, which dynamically impacts cancer cell proliferation, survival, and progression." (PMID 40809384, 2025). "However, due to the complex heterogeneity of tumors, the biological functions of METTL1 vary considerably across different cancer types." (PMID 41562049, 2025). "METTL1‐mediated m7G tRNA modification activates the WNT/β‐catenin signalling pathway in NPC to increase the translation of cyclins and associated oncogenes, including cyclin D1 and c‐Myc, thereby promoting the proliferation and migration of cancer cells." (PMID 39979979, 2025). "In conclusion, substantial evidence corroborates that METTL1 may serve as a driving force in cancer metastasis." (PMID 39979979, 2025). "Furthermore, Studies have shown that METTL1 is upregulated in various cancers, with its levels correlating with cancer malignancy." (PMID 40823093, 2025). "The functional roles of METTL1 in various types of human cancers." (PMID 39979979, 2025). "METTL1 knockdown inhibits cancer progression in xenograft mouse models and zebrafish cancer models." (PMID 41208200, 2025). "Several studies have demonstrated that METTL1 may serve as a robust biomarker of cancer prognosis and function as a potential therapeutic target." (PMID 40809384, 2025). "The highly heterogenous expression profile of METTL1 in various cancers suggests that it may serve as a biomarker of cancer progression and a target for therapeutic intervention." (PMID 40809384, 2025). "For instance, targeting METTL1 may have important therapeutic benefits on various cancers, particularly those characterized by high METTL1 expression, such as BLCA and HCC." (PMID 40809384, 2025). "This study reveals the importance of m7G methylation of tRNA in the stress response and suggests that targeting METTL1 may increase cancer sensitivity to chemotherapy." (PMID 39850560, 2024). "Furthermore, the knockdown of GADD45A consistently attenuated the anti-cancer phenotypes mediated by METTL1 overexpression in BC, including cell proliferation, migration, invasion, and apoptosis." (PMID 38822363, 2024). "Loss of METTL1 and WDR4 impairs cancer cell growth, tumorgenesis, and malignant transformation." (PMID 39850560, 2024).
cancer (continued). "METTL1 was negatively correlated with MSI and TMB in COAD but positively correlated with markers of HNSC, KICH, PRAD, and STAD, suggesting that METTL1 may have an impact on ICB therapeutic response in cancers such as HNSC." (PMID 39289775, 2024). "METTL1 regulates the N7-methylation of tRNA, affecting the survival of cancer cells under stress." (PMID 39850560, 2024). "In cancer, METTL1 is frequently overexpressed in inducing oncogenic cell transformation." (PMID 39006762, 2024). "Therefore, we overexpressed PTPN13 expression to counteract the cancer‐promoting effects of the overexpressed METTL1 and FOXM1." (PMID 38967523, 2024). "Overexpression of METTL1/WDR4 leads to malignant transformation and tumorigenesis, promote cancer progression, and may be highly associated with m7G methylation modification of tRNAArgTCT-4-1." (PMID 39019857, 2024). "Furthermore, in head and neck squamous cell carcinoma, METTL1 accelerates cancer progression by promoting the translation of cell cycle proteins and related oncogenes through the PI3K/AKT/mTOR signaling pathway." (PMID 39006762, 2024). "METTL1 knockout alters the link between cancer cells and their microenvironment in HNSCC." (PMID 39440068, 2024). "Because 5′TOGs can re-programme the translation machinery to favour the translational programmes required for cancer cells, we next investigated whether translational changes in METTL1 KO cells were mediated by the increased biogenesis of 5′TOGs." (PMID 37516825, 2023). "Altogether, our data suggested that METTL1 inhibition in cancer cells may stimulate a cytotoxic and anti-tumoural inflammatory response in the TME." (PMID 37516825, 2023). "In addition, m7G genes such as EIF4E2, DCPS, WDR4, and METTL1 were highly correlated with RARA-AS1 in multiple types of cancer (greater than 10 types)." (PMID 37833349, 2023). "Here, we report that METTL1 depletion leads to autophagy inhibition, elevated ROS production, and DNA damage, suggesting that combining METTL1 inhibitors with chemotherapy can improve therapeutic responses in cancer." (PMID 37660182, 2023). "By inhibiting METTL1-mediated methylation, we were able to increase the biogenesis of a novel class of ncRNAs (5'TOGs), which regulate the activation of the interferon signalling pathway in cancer cells." (PMID 37516825, 2023). "Additionally, METTL1 inhibition in cancer cells leads to increased infiltration of cytotoxic immune cells, which transforms the immunosuppressive prostate TME into a tumoricidal endotype." (PMID 37516825, 2023). "METTL1/WDR4 was reported to have a strong regulatory effect on cancer." (PMID 37006267, 2023). "METTL1 has been found upregulated in several tumours, yet, its expression in self-renewing cancer stem cells remains unknown." (PMID 37660182, 2023). "Furthermore,METTL1 has been reported to affect the viability of cancer cells, andWDR4 overexpression affects learning and memory in patients with Down syndrome." (PMID 36810782, 2023). "The expression of METTL1/WDR4 is abnormally elevated in most carcinomas, and by enhancing m7G tRNA expression, ribosome suspension is reduced, the efficiency of associated oncogenes’ mRNA translation is boosted, and downstream oncogenic signaling pathways like PI3K/AKT and MAPK are activated." (PMID 37710294, 2023). "METTL1, as an important methyltransferase, was reported to be overexpressed in many cancers." (PMID 36396627, 2022). "Based on the survival information from the TCGA database, we found that two (LGG and LIHC) of pan-cancer showed a highly consistent relationship between poor prognosis and high METTL1 expression; METTL1 expression in ACC, KIRC, and MESO is significantly related to OS, PFS, and DSS, instead of DFS." (PMID 35432338, 2022). "Our data uncovered the mechanism underlying mTOR overactivation in cancers and suggested that targeting mTOR/ULK1/autophagy could be an effective strategy for METTL1 overactive ESCC treatment." (PMID 35304469, 2022).